LCN2 (lipocalin 2)
Diseases named in the same sentence as LCN2 in open-access papers (continued):
Sharing a sentence is not in itself a finding about the gene and the disease.
hemorrhage (4 papers, 2017 to 2025). Loss of blood from the vascular compartment to the exterior or into nonvascular body space as a result of rupture or severance of the blood vessels. "Additionally, triple immunostaining with NeuN, MBP, and MAG confirmed that knocking out Lcn2 in microglia effectively enhances neuronal myelin recovery at the hemorrhage site during the chronic phase of ICH in mice." (PMID 40225581, 2025). "Based on this, during the induction of ICH in mice, Lcn2 inhibitors ZINC00784494 (ZINC-94), ZINC00640089 (ZINC-89), and the STAT3 agonist ML115 were administered for three consecutive days at the hemorrhage site to evaluate their effects on recovery during the chronic phase of ICH in mice." (PMID 40225581, 2025).
intestinal infection (4 papers, 2015 to 2024). "An increase in neutrophil infiltration as a result of intestinal infection is associated with increased biomarkers such as MPO and LCN-2." (PMID 35882715, 2022). "We can conclude that Lcn2 is a crucial component of mucosal immune defense against intestinal infection with E. coli K88." (PMID 29029438, 2017). "Furthermore, vascular endothelial B4galnt2 expressing animals (RIII+) exhibited increased Il-6 expression (Z = -1.932, P = 0.0528), but decreased LCN-2 production, suggesting a role for vascular B4galnt2 expression in the host immune response to intestinal infection." (PMID 26133982, 2015).
meningitis (4 papers, 2014 to 2023). A disorder characterized by acute inflammation of the meninges of the brain and/or spinal cord. "Increased levels of lipocalin 2 in cerebrospinal fluid may discriminate between acute bacterial and viral meningitis in patients with clinical syndrome of meningitis." (PMID 24885531, 2014). "We suggest that LCN2 detection in CSF from patients with clinical meningitis may help in differential diagnosis between acute bacterial and viral meningitis and may improve decision making for treatment algorithms in meningitis." (PMID 24885531, 2014).
metastatic disease (4 papers, 2014 to 2024). "Additionally, LCN2 is posited as a prospective prognostic biomarker, potentially signaling an increased metastatic disease risk among female smokers." (PMID 38672772, 2024). "The levels of LCN2 in serum and saliva are elevated in early stage BC patients and cancer-free females with a history of smoking, suggesting that LCN2 serves as a promising prognostic biomarker for predicting increased risk of metastatic disease in female smokers." (PMID 36294305, 2022). "Our bioinformatics results have shown that LCN2 is differently expressed in primary CRC, recurrent tumors, and metastatic tumors compared to non-tumoral samples." (PMID 35432477, 2022).
myelofibrosis (4 papers, 2021 to 2022). A partial or complete replacement of the bone marrow stroma by fibrous tissue. "Given the great interest in TGF-β1, LCN2, and CXCL1 in the pathobiology of myelofibrosis, the serum levels of these three inflammatory cytokines were compared by ELISA using larger cohorts of mice." (PMID 35204735, 2022).
myocardial ischemia (4 papers, 2015 to 2022). A disorder of cardiac function caused by insufficient blood flow to the muscle tissue of the heart. "It has been found that LCN-2 participates in the development of heart failure, myocardial hypertrophy, myocardial ischemia-reperfusion injury, chemotherapy-related cardiac function injury, and other heart diseases." (PMID 36419491, 2022).
Osteopenia (4 papers, 2020 to 2023). Osteopenia is a term to define bone density that is not normal but also not as low as osteoporosis. "In this way, an increase in lipocalin-2 was associated with an 80 to 81% increased risk of osteopenia and hip fracture." (PMID 36831188, 2023). "Notably, Lcn2 emerges as a complex player in bone biology, being detrimental for bone health when upregulated in hindlimb suspension and head-down tilt bed rest in mice and humans, respectively, but causing osteopenia in basal conditions when absent." (PMID 35055145, 2022). "In MDX mice, characterised by muscle damage and flogosis, the “pro-inflammatory” Lcn2 might be more important, and the osteopenia-inducing effect of the lack of Lcn2 is irrelevant compared to the damage it causes." (PMID 35055145, 2022).
periodontal disease (4 papers, 2014 to 2025). "LCN-2 is implicated in periodontal diseases, probably through the inflammation process." (PMID 39516276, 2025). "This systematic review suggests that LCN-2 is involved in periodontal diseases probably through inflammation, as LCN-2 levels increase in periodontal diseases and correlate with the type and severity of the condition." (PMID 39516276, 2025). "Evidence suggests that lipocalin-2 (LCN-2), a bone-derived protein, is upregulated in periodontal diseases." (PMID 39516276, 2025).
prediabetes (4 papers, 2012 to 2025). "Yet, baseline LCN2 levels could not predict the risk of type 2 diabetes in postmenopausal prediabetes women who were followed up for 5 years." (PMID 38035773, 2024).
proliferative diabetic retinopathy (4 papers, 2020 to 2025). Advanced retinopathy due to diabetes mellitus characterized by the formation of new vessels in the retina. "This study aims to assess the concentrations of LCN2 and vascular endothelial growth factor (VEGF) expressed in the vitreous humors of patients with proliferative diabetic retinopathy (PDR)." (PMID 32605546, 2020).
rhegmatogenous retinal detachment (4 papers, 2019 to 2025). Retinal detachment secondary to retinal tear or break. "In the existing literature, elevated LCN2 was also detected in the aqueous humor of patients with idiopathic acute anterior uveitis and central retinal vein occlusion and vitreous fluid from patients with rhegmatogenous retinal detachment." (PMID 32605546, 2020). "In a recent study, it has been demonstrated that a positive correlation between vitreous levels of LCN2 and proliferative vitreoretinopathy grading in patients with rhegmatogenous retinal detachment, revealing a potential role in the pathogenesis and progression of proliferative vitreoretinopathy." (PMID 32605546, 2020).
squamous cell carcinoma (4 papers, 2016 to 2023). A carcinoma arising from squamous epithelial cells. "The overall expression level of LCN2 was higher in the radioresistant squamous cell carcinomas (SCCs) than in the radiosensitive SCCs, in both the irradiated and untreated groups (P < 0.0001)." (PMID 33604288, 2020).
thalassemia (4 papers, 2010 to 2021). An inherited blood disorder characterized by a decreased synthesis of one of the polypeptide chains that form hemoglobin. "Additionally, two biomarkers (Lcn-2 and endocan-1) were identified as relevant biomarkers for the thalassemia patient population, which correlated differentially with specific blood parameters, and with a lipid (sub)class, namely ether PCs." (PMID 33530524, 2021).
Ventricular arrhythmia (4 papers, 2014 to 2024). "In this study, the functional relevance of Lcn2 in ventricular arrhythmia was investigated by preparing Lcn2+/+ and Lcn2−/− bone marrow chimeras resulting in bone marrow-derived cells, including neutrophils, lacking Lcn2." (PMID 38099844, 2024). "Although cardiac neutrophil counts were unaffected in Lcn2−/− bone marrow chimeras after MI, ventricular arrhythmia burden was reduced in Lcn2−/− bone marrow chimeras compared with Lcn2+/+ controls supporting the idea that Lcn2 contributes to arrhythmia burden in the ischemic myocardium." (PMID 38099844, 2024).
Abdominal obesity (3 papers, 2019 to 2023). Excessive fat around the stomach and abdomen. "MC4R and LCN2 mutations were detected in 2.42% and 0.84%, respectively, of Spanish children with abdominal obesity." (PMID 31035493, 2019). "Specifically, MC4R and LCN2 mutation carriers having abdominal obesity were able to reduce BMI-SDS after a lifestyle intervention." (PMID 31035493, 2019). "In summary, MC4R and LCN2 mutations were detected in 2.42% and 0.84%, respectively, of Spanish children with abdominal obesity." (PMID 31035493, 2019). "Our aim was to screen for mutations in the MC4R and LCN2 genes in a Spanish pediatric population with abdominal obesity." (PMID 31035493, 2019). "Against the background of abdominal obesity, the probability of having chronic bronchitis increased with an increase in the level of lipocalin-2 and GIP and TNFa." (PMID 36291711, 2022). "Among them, adiponectin, leptin, TNF-α, Factor D (adipsin), lipocalin-2 (NGAL), Serpin E1 (PAI-1), and CXCL8 (IL-8) were confirmed to have a positive correlation with central obesity (defined as WC)." (PMID 36768360, 2023).
alcoholic hepatitis (3 papers, 2020 to 2023). Acute hepatitis resulting from ingestion of alcohol. "Lcn2 has been investigated in alcoholic liver injury models as well as human alcoholic hepatitis." (PMID 34327512, 2021).
allergies (3 papers, 2015 to 2022). "Possible explanations for the gender-bias in allergics may be the link of LCN2 with iron, reflecting a lower iron-status of allergic women compared to the allergic men, causing part of the gender-bias in allergies." (PMID 30323863, 2018).
anxiety disorder (3 papers, 2016 to 2025). A category of psychiatric disorders which are characterized by anxious feelings or fear often accompanied by physical symptoms associated with anxiety. "Previous studies have shown that Lcn2 links peripheral inflammation to central nervous system (CNS) dysfunction, particularly in anxiety disorders." (PMID 40649841, 2025). "In summary, LCN2 acts on its receptor in mPFC neurons to disrupt neural activity, leading to anxiety disorders." (PMID 38589429, 2024). "Here, we identified a serum cytokine, lipocalin 2 (LCN2), that was upregulated in participants with anxiety disorders." (PMID 38589429, 2024). "Having observed the critical role of peripheral LCN2 in mediating anxiety disorders, we further examined the specific brain region that is responsive to LCN2 under CRS scheme." (PMID 38589429, 2024). "Our study did provide plausible evidence of LCN2 as a circulating biomarker for the diagnosis of anxiety disorders, although large cohort studies are needed for further substantiation." (PMID 38589429, 2024).
bile duct cancer (3 papers, 2021 to 2024). "LCN2 expression levels are particularly high in breast, pancreatic, ovarian, colorectal, thyroid, and bile duct cancer tissues and tumor cell lines." (PMID 39145770, 2024). "Overexpression of LCN2 has been observed in different types of cancer, such as breast, pancreas, ovarian, thyroid, colon, and bile duct cancers." (PMID 34445288, 2021). "Lipocalin-2 (LCN2) is a secreted glycoprotein that is abundant in aggressive subtypes of cancer, including breast, pancreas, thyroid, ovarian, colon, and bile duct cancers." (PMID 36897488, 2023).
Brain atrophy (3 papers, 2020 to 2022). Partial or complete wasting (loss) of brain tissue that was once present. "Theanine was suggested to prevent stress-induced brain atrophy by modifying early stress responses such as Npas4 and Lcn2." (PMID 31936294, 2020). "Since Lcn2 protein increases the sensitivity of neuronal cells to cell death, long-lasting Lcn2 overexpression may be a reason for brain atrophy and stress vulnerability in SAMP10 mice." (PMID 31936294, 2020).
cardiomyopathy (3 papers, 2016 to 2021). A disease of the heart muscle or myocardium proper. "Except the significant role that LCN2 seems to play in renal disorders, studies on cardiomyopathies indicate a wider role of LCN2." (PMID 27729871, 2016).
chronic hepatitis C (3 papers, 2016 to 2021). "Similarly, the quantities of LCN2 in fresh spot urine samples were found to correlate with fibrosis score and reflected the increased activity of matrix metalloproteinase-9 (MMP-9) in urine in patients suffering from chronic hepatic C infection." (PMID 27729871, 2016).
clear-cell renal cell carcinoma (3 papers, 2013 to 2023). "LCN-2 expression was analysed at the mRNA and protein level by using immunohistochemistry, RNAscope® and qRT-PCR in patients diagnosed with clear-cell renal cell carcinoma compared with adjacent healthy tissue." (PMID 31772326, 2020). "We aimed at clarifying the role of lipocalin-2 (LCN-2) in clear-cell renal cell carcinoma (ccRCC)." (PMID 31772326, 2020).
co-infection (3 papers, 2021 to 2025). "Co-infection of Salmonella with a Salmonella “probiotic” strain that is neither virulent nor capable of consuming F-Asn (a SPI1 SPI2 fraR-BDAE ansB mutant) led to a dramatic 10,000-fold reduction in CFU and a 1000-fold reduction in lipocalin-2, a proxy marker of inflammation." (PMID 41474808, 2025).
coronary atherosclerosis (3 papers, 2013 to 2023). Atherosclerosis of the coronary vasculature. "In addition, serum LCN2 levels are positively associated with the subsequent development of CAD in patients with coronary artery atherosclerosis." (PMID 24359145, 2013). "If we look at the average values of lipocalin-2 in healthy people and people with coronary atherosclerosis, it can be noted that in our study the level of lipocalin-2 was several times higher, which is consistent with the generally accepted data on its pro-inflammatory properties." (PMID 37240282, 2023). "In a recent study on patients with coronary atherosclerosis, against the background of both normal and overweight patients, we obtained data that significantly higher levels of lipocalin-2 were found in patients with coronary atherosclerosis compared to patients with normal coronary arteries." (PMID 37240282, 2023). "Further studies are needed to study lipocalin-2 and GLP-1 in patients with coronary atherosclerosis in this patient population." (PMID 37240282, 2023).
cystic fibrosis (3 papers, 2014 to 2023). Autosomal recessive disorder caused by pathogenic variants in the CFTR gene (cystic fibrosis transmembrane conductance regulator), which encodes a chloride and bicarbonate channel expressed in epithelial cells, and follow the diagnosis criteria. "In line with our findings, oral administration of vitamin D during 12 weeks to cystic fibrosis patients did not affect circulating levels of hCAP18/LL-37 and LCN2." (PMID 26545199, 2015).
delirium (3 papers, 2021 to 2025). A disorder characterized by confusion; inattentiveness; disorientation; illusions; hallucinations; agitation; and in some instances autonomic nervous system overactivity. "Our investigation reveals that elevated preoperative CSF LCN-2 levels are associated with the development of postoperative delirium in older adults undergoing hip fracture surgery." (PMID 41018204, 2025). "These correlations indicate that higher preoperative central LCN2 levels are not only predictive of POD occurrence but are also linked to a more severe clinical presentation of delirium." (PMID 41018204, 2025). "Furthermore, within the POD cohort, preoperative CSF LCN2 concentrations correlated positively with both delirium severity, as measured by the MDAS score, and levels of the proinflammatory cytokine IL-6 in the CSF." (PMID 41018204, 2025). "Animal models of hip fracture could be employed to mechanistically dissect how LCN2 contributes to neuroinflammation and delirium-like behaviors, providing a crucial bridge from clinical observation to molecular pathophysiology." (PMID 41018204, 2025). "Severe delirium was associated with rising trends in the serum levels of inflammatory markers, e.g., TNF-Alpha (p = 0.084 at 24 h and p = 0.087 at 72 h), Interleukin-8 (p = 0.032 at 24 h and p = 0.082 at 72 h), and Lipocalin-2 (p = 0.004 at 24 h and p = 0.078 at 72 h) in all studied subjects." (PMID 38136021, 2023).
encephalitis (3 papers, 2017 to 2020). An acute inflammatory process affecting the brain parenchyma. "In contrast, LCN2 was almost absent or detected at very low levels in CSF of patients with anti-NMDAR encephalitis (median, 0.9 ng/mL; range, 0.2–27.8 ng/mL) or without CNS infection (median, 0.2 ng/mL; range, 0.2–120.3 ng/mL)." (PMID 32659386, 2020). "However, previous studies only focused on quantifying LCN2 concentrations in patients with confirmed BM and viral encephalitis, and did not compare the performance of LCN2 against commonly used CSF markers such as leukocytes, glucose, protein and lactate." (PMID 32659386, 2020).
epilepsy (3 papers, 2020 to 2023). A brain disorder characterized by episodes of abnormally increased neuronal discharge resulting in transient episodes of sensory or motor neurological dysfunction, or psychic dysfunction. "High levels of expression of Lcn2 have been reported in several forms of epilepsy and the levels of Lcn2 in blood or cerebrospinal fluid (CSF) could be used as biomarkers of the progression of the disease." (PMID 32521797, 2020).
gastritis (3 papers, 2012 to 2025). Inflammation of the stomach. "Lipocalin 2 protein expression has been previously shown to increase in humans with gastritis in response to H. pylori infection." (PMID 23185574, 2012). "In particular, LCN2 expression levels were higher in MUC6+, MUC5AC+, proliferation cells, and in the chief cells in pre-GC and GC than gastritis." (PMID 40520011, 2025).
Granuloma (3 papers, 2019 to 2021). A compact, organized collection of mature mononuclear phagocytes, which may be but is not necessarily accompanied by accessory features such as necrosis. "We will construct LCN2 knockout mice to observe the effect of LCN2 on liver damage, granulomas, and fibrosis induced by schistosomiasis infection." (PMID 34616693, 2021). "Upregulation of HO-1 and Lcn-2 in granulomas of WTC dust-exposed patients may reflect a compensatory attempt to limit inflammation and granuloma progression." (PMID 30845693, 2019).
head and neck squamous cell carcinoma (3 papers, 2016 to 2022). A squamous cell carcinoma that arises from any of the following anatomic sites: lip and oral cavity, nasal cavity, paranasal sinuses, pharynx, larynx, and salivary glands. "LCN2 has also been shown to be unrelated to the metastasis of head and neck squamous cell carcinoma." (PMID 36428800, 2022).
Klebsiella pneumonia (3 papers, 2010 to 2025). An pneumonia caused by infection with Klebsiella. "A recent report describes induction of lipocalin 2 in lung cells following infection with Klebsiella pneumonia and points to a toll-like receptor 4 (TLR4)-mediated induction pathway." (PMID 20633248, 2010). "Similarly, LCN2 (NGAL) limits bacterial growth by binding siderophores, and its critical role has been validated in infection models in which LCN2-deficient mice displayed markedly increased bacterial burden and mortality during Klebsiella pneumoniae pneumonia." (PMID 41369347, 2025).
liver dysfunction (3 papers, 2016 to 2023). "Accordingly, endogenous Cd24a+Lcn2+ LPCs were identified by integration of sc-RNA-sequencing and pathological datasets of liver dysfunction which indicates that LPCs produced by ductular reactions might also originate from the resident LPCs." (PMID 37784089, 2023). "Here, the proliferative activity of the resident LPCs was activated by the cocktail (CD24+LCN2+ LPCs), and their phenotypes and roles in liver dysfunction was characterized together with those of hepatocyte-derived LPCs (HepLPCs) and BEC-derived LPCs (BecLPCs)." (PMID 37784089, 2023). "Our previous study has shown that neutrophil-derived lipocalin-2 could serve as a potential biomarker to identify liver injury of AOSD and evaluate the severity of liver dysfunction in AOSD patients." (PMID 36357401, 2022).
lymphoma (3 papers, 2011 to 2023). A malignant (clonal) proliferation of B- lymphocytes or T- lymphocytes which involves the lymph nodes, bone marrow and/or extranodal sites. "We first suspected a link between Lcn2 and tumor cell ER stress when we found that among the genes most upregulated in murine A20 lymphoma cells following treatment with thapsigargin (Tg), a canonical inducer of ER stress, was Lcn2." (PMID 21649922, 2011).